MMP9 (matrix metallopeptidase 9)
Diseases named in the same sentence as MMP9 in open-access papers (continued):
Sharing a sentence is not in itself a finding about the gene and the disease.
tumor (continued). "TANs promote angiogenesis at the invasive tumor front via a Matrix Metalloproteinase-9 (MMP-9) release, and chemokines such as CXCL1 and CXCL5 facilitate neutrophil infiltration, correlating with a poor prognosis." (PMID 40868256, 2025). "The EMT marker proteins, such as VIM, KRT18, KRT8, and MMP9 are involved in cell structure, motility, and matrix remodeling, which are crucial for tumor invasion and metastasis." (PMID 39858010, 2025). "MMP-9 also promotes angiogenesis, facilitating tumor growth and intravasation, ultimately leading to distant metastasis." (PMID 40284474, 2025). "MMP-9, frequently overexpressed in certain cancer types, plays a crucial role in tumor microenvironment remodeling." (PMID 40284474, 2025). "For validation, we immunoprecipitated MMP9 from a tumour excision and analyzed it by mass spectrometry." (PMID 41041068, 2025). "In this context, LCN2 interacts with MMP-9, stabilizing it and effectively exerting higher gelatinolytic activity on the extracellular matrix, enhancing matrix degradation, tumor progression and metastasis in BC." (PMID 41303420, 2025). "Sera MMP-9 can therefore serve as an individual baseline level for follow-up, since an increase should raise suspicion of tumor recurrence." (PMID 41573658, 2025). "Enhanced permeability: MMP-9 increases tumor blood vessel and tissue permeability, enhancing nanoparticle penetration into the tumor tissues." (PMID 40284474, 2025). "Previous studies have confirmed that the MMP-9 protein promotes tumor migration by degrading EMC or the linker complex between cells." (PMID 40034591, 2025). "For example, the PROS1-AXL pathway mediates the interaction between MICA+ tumor cells and MMP9+ macrophages, to facilitate tumor immune escape in advanced HCC." (PMID 39981249, 2025). "MMP9 facilitates tumour invasion and metastasis through the degradation of the extracellular matrix." (PMID 40475773, 2025). "The expression of N-cadherin and MMP9, which are related to tumor metastasis, was also significantly decreased in tumors from mice in the antibody treatment group compared to those in the untreated group (* p < 0.05; ** p < 0.001)." (PMID 40430040, 2025). "Matrix metalloproteinases (MMPs), particularly MMP-2 and MMP-9, play a critical role in cancer progression by degrading the extracellular matrix, thereby facilitating tumor growth and metastasis." (PMID 40563423, 2025). "In breast cancer cells, activation of TLR2 and TLR4 stimulates NF-κB, regulating the secretion of cytokines such as IL-6, TGF-β, VEGF, and MMP9, promoting tumor invasion, migration, and progression." (PMID 41200171, 2025). "In particular, MMP-9 degrades ECM components, promotes metastasis and tumor cell invasion, and serves as a potential diagnostic and prognostic biomarker." (PMID 41179295, 2025). "NO enhances MMP-2 and MMP-9 expression while concurrently downregulating tissue inhibitors of metalloproteinases (TIMPs)−2 and −3, thereby facilitating tumor invasion." (PMID 41036604, 2025). "Within the tumor microenvironment, MMP-9 activation of the nanovesicle surface peptides increased their uptake, and they subsequently released siRNAs and chemotherapeutic drugs to effectively inhibit non-small cell lung cancer growth." (PMID 40284474, 2025). "NE also activates MMP-9 via inactivation of natural gelatinase inhibitors (TIMPs) and thus indirectly influences the migratory abilities of tumor cells." (PMID 40155451, 2025). "Active neutrophil elastase (NE) and MMP9 in NETs hydrolytically remodel LN, exposing specific epitopes that bind to dormant tumor cells, awakening them and initiating proliferation." (PMID 40568594, 2025). "Stromal cells, including CAFs and tumor-associated macrophages (TAMs), secrete MMP2 and MMP9, driving ECM degradation." (PMID 39940643, 2025). "Existing studies have reported that PI3K/AKT signaling can upregulate MMP9 expression, further enhancing tumor dissemination." (PMID 41179295, 2025).
tumor (continued). "Extracts after in vitro digestion of wafers enriched with almond peel showed the presence of piceatannol 3-O-glucoside, which can inhibit the activity of matrix metalloproteinase (MMP)-9, which damages the extracellular matrix and promotes tumor growth." (PMID 41515425, 2025). "IHC was used to analyze the levels of Ki67, MMP-2, MMP-9, and Cleaved-caspase 3 proteins in each group’s tumor tissues." (PMID 39508798, 2025). "Recently, Cai's work reported that CTNNB1 activates MMP9 to induce a suppressive tumour immune microenvironment." (PMID 40111059, 2025). "Invadopodia of tumor cells are rich in MMP2 and MMP9, and these protrusions serve as crucial structures enabling tumor cell invasion." (PMID 41463642, 2025). "The data suggested that the upregulation of circ-NOLC1 suppressed the expression of Ki-67 and MMP9 in the tumor tissues from the CC mouse model." (PMID 40533863, 2025). "This has been documented in ESC and is increasingly recognized in EAC, where MC-derived VEGF-A and MMP-9 enable both endothelial cell recruitment and extracellular matrix remodeling, paving the way for invasive tumor growth." (PMID 40871387, 2025). "When LINC01016 is overexpressed, the binding of EIF4A3 and MMP9 mRNA is blocked, and NMD is inhibited, leading to the upregulation of MMP9, thus promoting tumor progression." (PMID 39881131, 2025). "MMP9 has been proven to promotes tumor invasion and metastasis by degrading extracellular mechanisms and basement membrane." (PMID 41312374, 2025). "Once released from tumor cells, MMP-9 can be detected in body fluids such as blood, urine, and cerebrospinal fluid (CSF) even before clinical symptoms appear." (PMID 41573658, 2025). "These macrophages overexpress MMP9 to promote vascular leakage and tumor cell extravasation, effectively reducing hepatic metastatic resistance." (PMID 40564894, 2025). "GMDS-AS1 stabilizes SIRT1 mRNA by recruiting TAF15, leading to p65 deacetylation and reduced MMP-9 expression, acting as a tumor suppressor in LUAD." (PMID 40684184, 2025). "It has been observed that MMP9 exhibits high activity in advanced OC, and its increased expression plays a role in tumor cell migration, invasion, metastasis, and the development of ascites." (PMID 40108613, 2025). "MMP-9-targeted siRNA in a GBM mouse model led to decreased tumor invasion and improved survival compared to untreated controls." (PMID 40265458, 2025). "Magnetic nanoparticles with a surface-modified glucose oxidase layer amplified oxidative stress, promoting MMP-9 expression and facilitating tumor extracellular matrix degradation, which enhanced nanoparticle penetration and inhibited breast tumor growth." (PMID 40284474, 2025). "LINC01016 blocks the binding of EIF4A3 to MMP9 mRNA, thereby inhibiting EIF4A3-mediated NMD, leading to increased MMP9 mRNA and protein expression, and promoting tumor progression." (PMID 39881131, 2025). "Lastly, in the G3 tumor, aside from MMP9, 15 additional genes (five upregulated, 10 downregulated) had a P‐value of < 0.05." (PMID 39245631, 2025). "Matrix metalloproteinases, including MMP9, contribute to extracellular matrix remodeling, promoting tumor invasion and dissemination." (PMID 40429793, 2025). "ASC-derived sEVs and CM secretome promoted OC cell colony formation, invasion, and migration while upregulating tumor-associated signaling pathways, including TGFβ/Smad, p38MAPK/ERK1/2, Wnt/β-catenin, and MMP-9." (PMID 40072102, 2025). "CXCL8 and CXCL10 promote ECM degradation by inducing overexpression of MMP-2 and MMP-9, thereby creating a gateway for tumor cell invasion." (PMID 41445742, 2025). "Compound 17, which exhibited cytotoxicity against PANC−1 cells, was linked to 55 targets, including key targets such as EGFR, AKT1, CDK1, CDK2, MMP9, PIK3CG, and TERT, closely associated with tumour cell proliferation, migration, and apoptosis." (PMID 41006588, 2025).
tumor (continued). "Elevated N-cadherin enhances cell motility, while MMP9 degrades the extracellular matrix, facilitating tumor invasion." (PMID 41472816, 2025). "This inhibition decreases the expression of key tumor-promoting factors like IL-6, VEGFα, MMP2, and MMP9, limiting the tumor-promoting environment created by TAMs." (PMID 40330466, 2025). "The results of this complex network model highlight the importance of exploring alternative approaches to target the enzymatic activity of tumour-associated MMP2 and MMP9." (PMID 40259907, 2025). "Western Blotting also demonstrated an increased expression of MMP7/MMP9 in TNBC tumor tissues of obese mouse in the HFD group." (PMID 40841364, 2025). "Intratumoral migrasome-rich fibroblasts activated B regulatory pathways via dual IL-10/TGFβ signaling, whereas juxta-5μm low-migrasome counterparts facilitated stromal-tumor cooperativity through MMP9/VEGF-A axis activation." (PMID 40443671, 2025). "Doxorubicin-conjugated RGD peptide nanoparticles, responsive to MMP-9 and pH, transformed from spheres to rods in the tumor environment, enhancing penetration and doxorubicin release and inducing apoptosis." (PMID 40284474, 2025). "VEGF can also be produced in the ECM by matrix metalloproteinase-9 (MMP-9) to activate an angiogenic switch that supports tumor proliferation." (PMID 41020852, 2025). "This was attributed to increased tumor-cell death and decreased tumor-derived MMP-9 and vascular endothelial growth factor expression." (PMID 40471394, 2025). "Together, these results suggest that Myr-NE treatment results in efficient inhibition of PAM proteins and VEGFR2 accompanied by significant downregulation of HIF-1α, Ki67, and MMP9 proteins, effectively reducing the tumor proliferation in TNBC xenografts." (PMID 40552278, 2025). "Specifically, VEGF upregulates MMP-9 expression, while VEGF inhibition can suppress MMP-9 activity, ascites volume and tumor burden." (PMID 41009634, 2025). "Another significant group of factors is the matrix metalloproteinases (MMPs), such as MMP-9, which degrade the extracellular matrix to facilitate tumor cell invasion and metastasis." (PMID 40227814, 2025). "The proteolytically active MMP-9 plays a crucial role in collagen IV degradation and promotes tumor cell invasion." (PMID 41259528, 2025). "In this specific tumor subset MMP9, together with MMP2 and ZEB1, were more related to the metastatic subtype of this tissue." (PMID 40332096, 2025). "ADAMTS13 and MMP9 were co‐expressed in both precursor lesions and invasive tumor cells, with MMP9 showing a largely uniform expression pattern." (PMID 41211185, 2025). "The MMP gene family, widely implicated in tumor progression, has been well-characterized in NSCLC, particularly MMP2 and MMP9 which play pivotal roles in metastasis and invasion." (PMID 40666104, 2025). "Many therapeutic targets—such as GAD1, DAD1, and MMP9—are also expressed in normal tissues, raising concerns about off-tumor toxicity." (PMID 41050070, 2025). "Experimental models consistently show that MMP-9 overexpression accelerates tumor progression, whereas genetic deletion or pharmacologic inhibition suppresses invasion and reduces metastatic burden." (PMID 41304763, 2025). "Both Sivelestat, an NE inhibitor, and GM6001, an MMP-9 inhibitor, affected major features of the metastatic tumor cell phenotype." (PMID 40155451, 2025). "Carboxymethyl chitosan has demonstrated the capability to diminish the levels of VEGF and MMP-9, thereby manifesting anti-tumor efficacy." (PMID 40821116, 2025).
tumor (continued). "As MMP13 can activate MMP9 by cleaving the inactive pro-MMP9 forms, its action on MMP9 activation facilitates tumour cell intravasation into vascular and lymphatic systems at primary tumour sites." (PMID 40243781, 2025). "VEGFR2-induced activation of the PI3K/Akt pathway stimulates the release of MMP9 and promotes tumor cell invasion and migration in TNBC cells." (PMID 40552278, 2025). "MMP-2 and MMP-9, known to promote tumor invasion and metastasis by degrading the extracellular matrix and basement membrane, were significantly downregulated in APOC1-knockdown cells, as shown by Western blot analysis (P < 0.0001)." (PMID 39873475, 2025). "Within the study, the authors found that COL1A1 and MMP9 were also amongst the most upregulated genes in tumor cells that were co‐cultured with CAFs." (PMID 39245631, 2025). "To analyze the neutrophil properties, we used the following frequently mentioned profiles: pro-tumor anti-inflammatory profile (Mmp9, Vegfa, Arg1, Nos2, Ccl17, Il10) and anti-tumor pro-inflammatory profile (Icam1, Tnfa)." (PMID 40001601, 2025). "Among them, MMP2 and MMP9 are also known as type IV collagenases, which are the most commonly expressed MMPs in tumor cells and are highly expressed in digestive system tumors." (PMID 40563539, 2025). "Another way by which neutrophils facilitate extravasation of tumor cells is the production and release of IL-1β, which activates the endothelium and results in concomitant MMP9 production, as shown in a mouse model of melanoma metastasis." (PMID 39653768, 2025). "It exerts its anti-tumour impact by downregulating MMP9 expression through the FAK/PI3K/AKT pathway and rectifies Th1/Th2 imbalance by blocking the p38 MAPK signalling pathway." (PMID 41353393, 2025). "The SAM and SH3 domain-containing 1 (SASH1) overexpression significantly inhibited cell invasion and proliferation by downregulation of MMP-2 and MMP-9, suggesting its tumor-suppresive role via the FAK-related axis." (PMID 41148856, 2025). "This generated a tumour-like stroma with higher levels of collagen 1, matrix metallopeptidase 9 (MMP-9) and tenascin C." (PMID 40801095, 2025). "Previous studies have shown that L. rhamnosus GG can limit tumor progression by reducing colorectal cell invasion through influencing MMP‐9 activity." (PMID 40791867, 2025). "According to our results, TA can inhibit numerous molecular targets associated with tumor growth and angiogenesis, including cytokines, COX-2, MMP-2/MMP-9, and VEGF." (PMID 41009634, 2025). "Specifically, MMP-2 and MMP-9 facilitate tumor metastasis by degrading components of the extracellular matrix, enabling the dissociation of cancer cells from the primary tumor and promoting invasive behavior." (PMID 41153831, 2025). "Increased expression of MMP9 protein degrades the extracellular matrix, affects angiogenesis, and promotes tumor infiltration and metastasis, driving the progression of EMT." (PMID 41472816, 2025). "We determined that LINC01016 can blocks the binding of EIF4A3 to MMP9 mRNA, thereby inhibiting EIF4A3-mediated nonsense-mediated RNA decay (NMD), increasing MMP9 mRNA level and protein expression levels to promote tumor progression." (PMID 39881131, 2025). "As an extracellular matrix component, while HA was localized in the stromal compartment, HAS-2, HYAL-1, Slug, MMP-9, and N-Cadh were expressed in tumor cells." (PMID 40149256, 2025). "Although MMP9 had minimal impact on baseline proliferation, it significantly attenuated FF’s efficacy, potentially due to its primary role in promoting tumor invasion and metastasis." (PMID 40630198, 2025). "PCSK9 reduces E-cadherin expression, increases N-cadherin levels, and enhances matrix metalloproteinase-9 (MMP9) activity, thereby promoting tumor cell migration and invasion." (PMID 40563628, 2025). "Next, the expression levels of Ki67 protein (a proliferation marker) and MMP9 protein (a migration marker) in the tumor tissues of the mice were analyzed using IHC." (PMID 40533863, 2025).
tumor (continued). "Among them, MMP-9 contributes to tumor cell migration and metastasis by degrading the extracellular matrix (ECM), regulating cell-cell and cell-ECM interactions, and releasing pro-invasive factors." (PMID 40424719, 2025). "PCa frequently exhibits elevated MMP-9 expression, which promotes metastasis by allowing tumor cells to penetrate through the bloodstream through the basement membrane." (PMID 40429793, 2025). "Taken together, the molecular mechanisms involved in the oncogenic and tumor-suppressive roles of LCN2 are associated with EMT, iron metabolism, the LCN2/MMP9 complex, and angiogenesis." (PMID 40109857, 2025). "The matrix metalloproteinase 9 (MMP-9) in NETs can inhibit tumor cell apoptosis, facilitating angiogenesis and tumour neovascularisation." (PMID 40239243, 2025). "They promote cancer growth by producing MMP-9, aiding angiogenesis, and forming neutrophil extracellular traps (NETs), which support tumor growth and metastasis in many cancer types." (PMID 40260236, 2025). "These neutrophils enhance PMN formation, facilitating tumor cell extravasation and proliferation through the upregulation of prometastatic proteins such as Bv8, MMP9, S100A8, and S100A9." (PMID 40470380, 2025). "Highly infiltrated M0 macrophages can increase extracellular matrix porosity by secreting pro-inflammatory factors such as L-8 and MMP9, thereby promoting tumor cell invasion and vascular extravasation." (PMID 41415282, 2025). "ERK1/2 phosphorylation pathway is activated, increasing MMP9 expression to enhance tumor invasiveness." (PMID 40708946, 2025). "These nanotherapeutic strategies leverage MMP-9 overexpression to achieve targeted drug release, improved tumor penetration, and reduced systemic toxicity." (PMID 40284474, 2025). "It has been reported that MDSCs can promote the invasive capacity of cancer cells via MMP9, thus enabling these cells to move from the primary tumor to metastatic sites." (PMID 41010517, 2025). "Upregulation of cytokines, chemokines, and enzymes (e.g., Matrix Metalloproteinase-9 (MMP9)) then facilitates tumor cell migration, invasion, and immune evasion." (PMID 41226481, 2025). "Our data reveal the parallel execution of tumor cytotoxic and prometastatic activity by activated neutrophils and identify NE and MMP-9 as mediators of lymph node metastasis." (PMID 40155451, 2025). "Our results suggest a critical role for MMP-9 in local invasion and tumor aggressiveness, particularly during the T2 and T3 stages, when the tumor breaches the basement membrane, invades local tissue, and stimulates neovascularization." (PMID 40729026, 2025). "In the MMPs family, the MMP-9 protein is found to exist in different types of cancer, and it is believed to facilitate tumor invasion, migration, and metastasis." (PMID 40034591, 2025). "Evidence of p-cymene-mediated inhibition of MMP-9 (matrix metalloproteinases) expression shows its anti-tumor activity." (PMID 40427657, 2025). "Tumor necrosis factor-α (TNF-α) serves as an additional upstream regulator; the RGD (Arg-Gly-Asp)-toxin peptide has been reported to inhibit TNF-α-induced MMP-9 secretion, resulting in suppressed tumor-cell proliferation." (PMID 41181710, 2025). "Mechanistically, our data reveal that knockdown of KRAS inhibits matrix metalloproteinase (MMP1), MMP3, and MMP9, which are known as tumor metastasis-related proteins, via an IL-17 signal-dependent manner." (PMID 40486048, 2025). "In particular, MMP-9 is a demonstrated driver of tumor progression in several types of cancer, including colorectal cancer, non-small cell lung cancer, triple-negative breast cancer, and others." (PMID 41154699, 2025). "The resulting peptide clamp is linked to the antibody via a protease-cleavable sequence sensitive to matrix metalloproteinases (MMPs), particularly MMP-2 and MMP-9, which are frequently overexpressed in the tumor microenvironment." (PMID 41246356, 2025).